MTOR (mechanistic target of rapamycin kinase)
Diseases named in the same sentence as MTOR in open-access papers (continued):
Sharing a sentence is not in itself a finding about the gene and the disease.
breast cancer (continued). "Additionally, curcumin has demonstrated its capacity to modulate several pivotal signaling pathways implicated in breast cancer progression and development, such as JAK/STAT, NF-κB, WNT/β-catenin, PI3K/Akt/mTOR, MAPK, apoptosis, and cell cycle pathways." (PMID 37569854, 2023). "The mammalian target of rapamycin (mTOR) regulates basic cellular processes, including protein synthesis and cell proliferation, growth, and metabolism, which plays a critical role in the progression of breast cancer." (PMID 36986711, 2023). "However, in some human cancers, such as breast cancer, PIK3CA mutation is considered a biomarker for predicting PI3K/AKT/mTOR pathway activity." (PMID 37046703, 2023). "BCAT1 knockdown may help reduce mTOR signaling and reduce the growth rate of breast cancer cell lines." (PMID 38028625, 2023). "In human breast cancer, mTOR activation in CSCs is important for colony-forming and tumorigenicity." (PMID 36816969, 2023). "Abnormal activation of the mTOR signaling pathway is present in 70% of breast cancer." (PMID 37277807, 2023). "However, the specific mechanism of mTOR in the occurrence and development of breast cancer is still unclear and requires further study." (PMID 37637052, 2023). "As mTOR pathways modulate cellular growth via estrogen receptor (ER) signaling and combined mTOR and ER inhibition previously demonstrated survival benefits in breast cancer, this exploratory study evaluates mTOR pathway and ER expression interactions in a preclinical cervical cancer model." (PMID 37623437, 2023). "mTOR is commonly activated in breast cancer and is a promising therapeutic target for the disease." (PMID 37711177, 2023). "Gene set variation analysis (GSVA) showed that CCL8 are positively correlated with gene sets related with hypoxia, glycolysis, mTOR, macrophage, M2 macrophage, negatively correlated with glucose starvation, M1 macrophage in invasive breast cancer samples, respectively." (PMID 37884960, 2023). "Our study expands the rationale for targeting the mTOR–proteasome axis in breast cancer therapies." (PMID 37589705, 2023). "However, most of these findings have been identified in in vitro models and/or by the use of preclinical mTOR inhibitors (mTORi); thus the in vivo and clinical relevance of these findings for breast cancer has remained elusive." (PMID 37642941, 2023). "Research in this field is mainly focused on the following aspects: the mechanism of mTOR signaling pathway in breast cancer development, the application and optimization of mTOR inhibitors in breast cancer treatment, and the role of mTOR signaling pathway in breast cancer drug resistance." (PMID 37637052, 2023). "Finally, we found that metformin inhibited the DPP-4 deficiency-stimulated mTOR/HIF-1α/autophagy axis and induced breast cancer apoptosis." (PMID 37760498, 2023). "Therefore, this study proposes the use of mTOR inhibitors as targeted therapies for CSCs and cancer cells in canine mammary cancers, similar to human breast cancers." (PMID 36816969, 2023). "The down-regulation of the mammalian target of rapamycin (mTOR) signaling pathway which has been demonstrated to be deeply involved in energy homeostasis could reduce CSCs in breast cancer." (PMID 37622118, 2023). "To establish whether LHX2 activates the PI3K/AKT/mTOR pathway and apoptosis pathway in breast cancer, we conducted a Western blotting assay to detect the signature proteins in these pathways, including PI3K, p-PI3K, Akt, p-Akt, Bcl-2, and Bax." (PMID 37345110, 2023). "In addition, MA promotes autophagosome formation by inactivating the RIP1-mediated AKT/mTOR signaling pathway and restrains autophagosome degradation by reducing lysosomal acidity, thus inducing secretory autophagy in breast cancer cells." (PMID 36976201, 2023). "Breast cancer tumour tissue reveals AKT1 and MTOR mutations." (PMID 36831624, 2023).
breast cancer (continued). "Phosphorylated mTOR expression in canine mammary tumors is associated with tumorigenesis and negative clinical behavior." (PMID 36816969, 2023). "In addition, OTUD5 knockdown has been shown to inhibit the proliferation of cancer cell lines with mutations that activate the mTOR pathway; these include HT29 colon cancer cells and MCF7 breast cancer cells." (PMID 37190070, 2023). "Further investigation into the possible roles that mTOR could play in this scenario could lead to future preventative measures in preventing breast cancer development." (PMID 37904250, 2023). "Rapamycin, an inhibitor of mTOR, decreased mammary tumor size and CSC activity." (PMID 37468874, 2023). "In addition, without activating ER-α, which causes female diseases such as breast cancer and uterine myoma, ER-β activated AMPK in the liver, the center of energy metabolism and autophagy, causing inhibition of mTOR, an indicator of aging and autophagy." (PMID 37435569, 2023). "The PI3K/AKT/mTOR signaling pathway is one of the most important molecular signaling pathways that modulate proliferation, survival, invasion, migration, apoptosis, glucose metabolism, and DNA repair in ER+ breast cancer cells." (PMID 36835458, 2023). "However, an mTOR inhibitor (everolimus) has been approved by the U.S. Food and Drug Administration for treatment of breast cancer." (PMID 37251941, 2023). "Additionally, the secretion of chemokine ligand 2 (CCL2) by TAMs triggers the activation of the PI3K/AKT/mTOR signaling cascade in tumor cells, culminating in tamoxifen resistance within breast cancer." (PMID 38001753, 2023). "Activation of the Akt/mTOR pathway, which regulates various cellular activities, including protein synthesis, metabolic regulation, cell survival, and differentiation, facilitates tumor growth and breast cancer cell survival." (PMID 37885013, 2023). "However, baicalin-induced autophagy through ROS/AKT/mTOR signaling has a harmful effect on breast cancer." (PMID 36678588, 2023). "Similar effects were also observed in canine mammary cancer cell lines that exhibit high basal Wnt/β-catenin activity, where treatment with dactolisib (dual pan-PI3Kα/γ/δ/β and mTOR inhibitor) enhanced TCF/LEF transcriptional activity, and CTNNB1 and AXIN2 mRNA expression." (PMID 37471270, 2023). "Another vulnerability in TNBC may lie in the PI3K/Akt/mTOR pathway, that plays a critical role in cell proliferation, survival, mobility, and chemotherapy resistance in breast cancer." (PMID 36979714, 2023). "The mechanism underlying our finding is unclear, but our results suggested that how PA influences mTOR pathway activation in human breast cancer may be more complex than in preclinical models." (PMID 36895729, 2023). "However, in a randomized trial of 32 overweight/obese patients with breast cancer, expression of PI3Kinase genes, upstream signaling of mTOR, significantly increased after aerobic exercise plus caloric restriction." (PMID 36895729, 2023). "Data suggest that cotargeting CDK4/6, PI3K/AKT/mTOR, and ERα could effectively control tumor growth in ER+ breast cancer xenografts and PDX models." (PMID 37725704, 2023). "In addition, other studies confirmed that EMT promoted tumorigenesis through the PI3K/Akt/mTOR signaling in colorectal cancer and brain metastasis of breast cancer that were reversed by treatment with mTOR inhibitor Rapamycin." (PMID 36910848, 2023). "The induction of Wnt/β-catenin signaling in ER− breast cancers with PI3K/mTOR inhibition suggests that Wnt activation may reduce the sensitivity of these breast cancers to PI3K inhibitors." (PMID 37471270, 2023). "Moreover, healthy people BMSC-derived exosomes can inhibit in vitro angiogenesis in breast carcinoma cells through miR100 by regulating the mTOR/HIF1α/VEGF signal transduction pathway." (PMID 37237420, 2023). "In addition, CE was found to activate the AKT/mTOR pathway and promotes tumor growth in breast cancer." (PMID 35646697, 2022).
breast cancer (continued). "Thus, upon mTOR inhibition, changes in AS events are maximized in the Tsc1-/- system compared to breast cancer cells." (PMID 36293270, 2022). "AKT/mTOR is highly activated in lapatinib-resistant HER2+ breast cancer cells." (PMID 36010585, 2022). "Furthermore, RBM8A silencing decreased the DDP resistance in breast cancer cells by inhibiting the AKT/mTOR pathway." (PMID 36105365, 2022). "Our primary objective was to determine the anti-tumor activity of cimetidine, vitamin C and their combination via targeting TAMC and its mediators (histamine, VEGF, and TNF-α) in the TME and investigating their effect on PI3K/AKT/mTOR cue in Ehrlich induced breast cancer in mice." (PMID 35798765, 2022). "However, no sufficient data is available on flavonoids targeting mTOR in chemoresistant breast cancer and thus, it is a future prospect to elaborate the role of flavonoids targeting mTOR in chemoresistant breast cancer." (PMID 35795855, 2022). "For these patients, S6K1 blockade using upstream mTOR inhibitor could increase the sensitivity of breast cancer to CDK4/6 inhibitor." (PMID 36042494, 2022). "The combined use of Huaier extract and TAM in vivo can enhance the inhibitory effects of TAM on the growth of subcutaneous tumors of MCF-7 breast cancer cells and synergistically induce autophagy and apoptosis in ER+ breast cancer cells via suppression of the AKT/mTOR pathway." (PMID 35721162, 2022). "Overwhelming such issue with this flavonoid might give fruitful outcome in the future during breast cancer therapy targeting the mTOR signaling pathway." (PMID 35795855, 2022). "Additionally, SNAT1 overexpression increases the phosphorylation level of Akt (p-Akt) and mTOR (p-mTOR) in osteosarcoma, breast cancer, and hepatocellular carcinoma (HCC)." (PMID 35565278, 2022). "Applying PI3K/AKT/mTOR axis inhibitors such as NVP-BEZ235 is a potential therapy for breast cancer." (PMID 36139919, 2022). "The microarray results suggested that the autophagy inducing effect of SCA in breast cancer cells might be related to its regulation of the PI3K–Akt–mTOR signaling pathway." (PMID 36408240, 2022). "The inducing effect of SCA on breast cancer autophagy was reversed by the mTOR activator MHY1485." (PMID 36408240, 2022). "However, TNFα upregulates mTOR activity in an NF-κB-dependent manner and inhibits autophagy in the human breast cancer MCF7 cell line." (PMID 35159248, 2022). "Moreover, CB2 activation in breast cancer also led to protein kinase B (AKT)/mammalian target of rapamycin (mTOR) inhibition." (PMID 35513484, 2022). "In addition to affecting the expressions of some pro-angiogenic factors such as HIF-1α, eNOS, and MMP-2/9, 4-CF can also inhibit the survival of human umbilical vascular endothelial cells and breast cancer cells by inhibiting the PI3K/AKT/mTOR pathway." (PMID 36104717, 2022). "Randomized clinical trials have demonstrated that PI3K/AKT/mTOR inhibitors bring significant clinical benefit to patients with advanced breast cancer, especially to those with hormone receptor (HR)‐positive, human epidermal growth factor receptor (HER) 2‐negative advanced breast cancer." (PMID 38089455, 2022). "Among these, mTOR signaling was found a potent therapeutic target for flavonoids in breast cancer." (PMID 35795855, 2022). "Furthermore, a combination of WDR5 targeting with mTOR inhibitors leads to potent suppression of translation and proliferation of breast cancer cells." (PMID 36043466, 2022). "Overexpression and activation of AKT and mTOR, as sub-pathways of EGFR, are directly linked to the development of breast cancer, and we demonstrated that n-10 fatty acids have an impact on these two signaling proteins, in connection with but also independently from EGFR." (PMID 35053341, 2022). "Therefore, the inhibition of mTOR not only has a therapeutic effect but also reduces HIF-1α expression in breast cancer." (PMID 35413842, 2022).
breast cancer (continued). "Collectively, these findings strongly support our hypothesis that ATRAP performs an oncogenic role in breast cancer progression via activation of AKT/mTOR signaling in vivo." (PMID 35414770, 2022). "SOX2 has been illustrated to increase cellular proliferation, colony formation, and metastasis by promoting WNT/β-catenin signaling and epithelial-mesenchymal transition (EMT) and downregulating AMP-activated protein kinase/mTOR signaling in breast cancer cells." (PMID 35402219, 2022). "Additionally, growth determination following cells transfection with mTOR siRNA showed 25% and 35% decrease in cell number after 48 and 72 h, respectively, suggesting that the transient knockdown of mTOR inhibits the breast cancer cell growth." (PMID 36135836, 2022). "Therefore, the USF1/ATRAP/PBX3 axis activates AKT/mTOR signaling and promotes breast cancer aggressiveness." (PMID 35414770, 2022). "At present, a lot of novel aurora kinase inhibitors only have effects on aurora A, such as MLN-8237, which has been found to promote the apoptosis and autophagy of breast cancer cells by regulating the p38 MAPK/Akt/mTOR pathway and has entered the second phase of clinical trials." (PMID 35311116, 2022). "Temsirolimus and everolimus are FDA-approved mTOR inhibitors for kidney or breast cancer." (PMID 35681641, 2022). "Our novel finding that NPC1 silencing can suppress P70-S6K signaling in some breast cancer cell lines suggests that mTOR may link lysosomal cholesterol with mitochondria in these cells." (PMID 35884604, 2022). "In addition, quercetin showed its anti-breast cancer effect via inhibiting the Akt/AMPK/mTOR signaling cascade." (PMID 36233051, 2022). "In addition, miR-21 also inhibits breast cancer cell autophagy through the PI3K/AKT/mTOR pathway and sensitivity to chemotherapeutic drugs." (PMID 35883139, 2022). "Similarly, eight flavonoids isolated from Tephroseris kirilowii were evaluated for breast cancer treatment focusing on the mTOR signaling pathway." (PMID 35795855, 2022). "Mechanically, we examined whether the reduced level of AGO2 due to UA could inactivate FAK/PI3K/Akt/mTOR signaling that retarded cell migration and invasion of breast cancer cells." (PMID 36613808, 2022). "Another study showed that mTOR-dependent selective translation of mRNAs that are important in cell proliferation, survival, and genomic reprogramming confers tamoxifen resistance and estrogen independence in breast cancer cells." (PMID 36259537, 2022). "Thus, the effect of mTOR regulation on polyamine content in the breast cancer cells was also examined using transient knockdown of mTOR gene by mTOR siRNA." (PMID 36135836, 2022). "Tanshinone IIA inhibited the breast cancer cell line MCF-7 growth by inhibiting the mammalian target of rapamycin (mTOR), phosphatidylinositol-3-kinase (PI3K), mitogen-activated protein kinase (MAPK) signalling pathway protein kinase B (Akt), and protein kinase C (PKC)." (PMID 35897965, 2022). "Additionally, PI3K/Akt/mTOR signaling pathway is aberrantly activated in human melanoma, breast cancer, lung cancers, and other tumors." (PMID 36104717, 2022). "Moreover, SPOCK1 is reported promoting the proliferation and migration in many other cancers like colon cancer, pancreatic cancer and breast cancer via NF-κB pathway or AKT/mTOR pathway." (PMID 35360859, 2022). "Moreover, ivermectin inhibits the serine/threonine kinase (AKT)/mammalian target of rapamycin (mTOR) signaling pathway in breast cancer." (PMID 36091811, 2022). "This has been demonstrated by treating human breast cancer cells with tetrandrine or the known autophagy inducer Rottlerin, which promotes the cell death of breast cancer stem cells by mediating the suppression of Akt and mTOR signaling, and the up-regulation of phospho-AMPK." (PMID 35884904, 2022).
breast cancer (continued). "Consequently, add-on drugs that target the resistance mechanisms, such as the PI3K inhibitor alpelisib and the mTOR inhibitor everolimus, have shown promising results in clinical trials for advanced ER+ breast cancers." (PMID 36304922, 2022). "AKT/mTOR inhibition in breast cancer cell lines leads to decreased FOXP1 expression." (PMID 35122700, 2022). "Furthermore, it was shown that inhibition of leucine uptake suppresses mTOR signaling and promotes apoptosis in breast cancer cell lines." (PMID 34921655, 2022). "However, further in-depth studies on other molecular mechanisms and downstream targets of ER and PI3K/AKT/mTOR need to be elucidated to fully explain the inhibitory effect of andrographolide in breast cancer cells." (PMID 35684480, 2022). "The PI3K/mTOR network has detected actionable target proteins in breast cancers." (PMID 36559135, 2022). "Also, in another preclinical study, the combination of T-DM1 with PI3K/mTOR inhibitors enhanced its anti-tumor activity in breast cancer lines in vitro and as xenografts in vivo." (PMID 36033955, 2022). "Therefore, ATRAP can improve glucose consumption and lactate production by activating the AKT/mTOR pathway, and providing energy to promote the growth and metastasis of breast cancer cells." (PMID 35414770, 2022). "Human epidermal growth factor receptor-2 (HER2) is involved in the development of breast cancer through the PI3K/Akt/mTOR pathway, and the PI3K/Akt/mTOR pathway is an important pathway involved in chemoresistance and survival of triple-negative breast cancer (TNBC)." (PMID 35251175, 2022). "This review article is aimed at highlighting the role of the mTOR signaling pathway in breast cancer, the potential role of flavonoids in breast cancer therapy targeting the mTOR signaling pathway, and resistant breast cancer as well, exposing mTOR as therapeutic target for flavonoids." (PMID 35795855, 2022). "In addition, ATRAP can function as an oncogene through activation of the AKT/mTOR pathway in breast cancer." (PMID 35414770, 2022). "Indeed, the benefits of mTOR inhibition have been demonstrated in the clinical treatment of breast cancer, indicating the centrality of this anabolic master switch for the both the prevention and combatting of cancer." (PMID 36388131, 2022). "Thus far, only a few PI3K and mTOR inhibitors have been approved for the treatment of breast cancer." (PMID 36010585, 2022). "In another study, it was reported that IVM could activate autophagy by the blockade of the Akt/mTOR signaling pathway in various breast cancer cells." (PMID 35624772, 2022). "Recent studies have shown that mTOR is a therapeutic target in breast cancer." (PMID 35795855, 2022). "mTOR inhibitors were the first treatment class to be licensed and everolimus has shown clinical benefit when given in combination with exemestane for metastatic ER+ breast cancer." (PMID 36046843, 2022). "The stimulatory role of mTOR signaling in SREBP-1 expression in breast cancer cells was confirmed by demonstrating that rapamycin, a pharmacological inhibitor of mTOR, markedly decreased SREBP-1 expression, whereas activation of mTOR by treatment with MHY1485 enhanced expression levels of SREBP-1." (PMID 34986886, 2022). "Recently, it was reported that the mammalian target of rapamycin (MTOR, a serine- threonine kinase of the phosphatidylinositol (PI) kinase-related protein kinase family) is activated in various carcinoma cells, including breast cancer, ovarian cancer, and HCC." (PMID 35159256, 2022). "Insulin and IGF signaling are implicated in breast cancer tumorigenesis and IGF binding to its receptor and subsequent autophosphorylation leads to phosphorylation of IR substrate-1 (IRS-1) and activation of the PI3K/Akt/mTOR pathway." (PMID 36046843, 2022).